ADCK1 (aarF domain containing kinase 1)
Description:
Appears to be essential for maintaining mitochondrial cristae formation and mitochondrial function by acting via YME1L1 in a kinase-independent manner to regulate essential mitochondrial structural proteins OPA1 and IMMT. The action of this enzyme is not yet clear (Probable). It is not known if it has protein kinase activity and what type of substrate it would phosphorylate (Ser, Thr or Tyr) (Probable).
Synonyms: FLJ39600; MCP2
Tractability: Small molecule: a high-quality ligand is known. PROTAC: ubiquitination databases record sites on it; its protein half-life has been measured; a small molecule that binds it is known.
Target class: Enzyme; Transferase
Gene: Protein-coding gene on chromosome 14 (77,800,064 to 77,935,014, forward strand). Ensembl gene ENSG00000063761.
Subcellular location: Mitochondrion
Subcellular location (Human Protein Atlas): Nucleoplasm
Gene Ontology:
Biological process: negative regulation of mitochondrial fusion; positive regulation of cristae formation; lipid homeostasis; mitochondrion organization
Cellular component: mitochondrion; mitochondrial inner membrane
Genetic constraint (gnomAD): Loss-of-function variants: 36 observed, 51.92 expected, observed/expected ratio (o/e) 0.69, 90% interval 0.53 to 0.92. The upper end of that interval is the gene's LOEUF score, 0.92, which puts it in group 3 of 6, group 1 being the genes least tolerant of losing a copy. Missense variants: 581 observed, 619.25 expected, observed/expected ratio (o/e) 0.94, 90% interval 0.88 to 1. Synonymous variants: 223 observed, 259.07 expected, observed/expected ratio (o/e) 0.86, 90% interval 0.77 to 0.96.
Homologues: Orthologues: chimpanzee ADCK1 (99% identical), macaque ADCK1 (98% identical), dog ADCK1 (92% identical), guinea pig ADCK1 (90% identical), mouse Adck1 (88% identical), rat Adck1 (88% identical), rabbit ADCK1 (81% identical), pig ADCK1 (73% identical), zebrafish adck1 (69% identical), tropical clawed frog adck1 (64% identical), Drosophila melanogaster Adck1 (45% identical), Caenorhabditis elegans D2023.6 (43% identical). Paralogues in human: ADCK5 (36% identical), COQ8A (20% identical), COQ8B (20% identical), ADCK2 (19% identical).
Diseases named in the same sentence as ADCK1 in open-access papers:
ADCK1 is named in the same sentence as 21 diseases in open-access papers, as found by Europe PMC text mining. Sharing a sentence is not in itself a finding about the gene and the disease. The quoted sentences say what the papers report.
colon cancer (4 papers, 2021 to 2025). "In colon cancer, ADCK1 has been associated with pro-cancerous effects through its interaction with the β-catenin/TCF signaling pathway." (PMID 40565246, 2025). "Research has revealed that ADCK1 gene overexpression in colon cancer and osteosarcoma contributes to tumour cell growth." (PMID 41017026, 2025). "The role of ADCK1 in colon cancer underscores its significant oncogenic potential, positioning it as a promising therapeutic target for future treatment strategies." (PMID 40565246, 2025). "In vitro studies have demonstrated that the increased expression of ADCK1 in colon cancer cell lines enhances their ability to form colonies and increases their invasive potential." (PMID 40565246, 2025). "Research indicates that ADCK1 expression is upregulated in colon cancer patients and is negatively correlated with patient survival." (PMID 40565246, 2025). "ADCK1 silencing, by the shRNA strategy, potently inhibited colon cancer cell colony formation and infiltration as well as the in vivo tumorigenesis, migration, and organoid formation." (PMID 36371387, 2022). "To study the expression pattern of ADCK1 in colon cancer, we first searched the HPA (Human Protein Atlas) database and studied the relationship between ADCK1 expression in colon cancer patients and patient survival." (PMID 33824271, 2021). "In conclusion, our research revealed the functions of ADCK1 in the development of colon cancer and provided potential therapeutic targets." (PMID 33824271, 2021). "We next examined the expression of ADCK1 using a tissue array that contained 77 normal colon epithelial tissues and 100 colon cancer samples." (PMID 33824271, 2021). "In this study, we examined the expression of ADCK1 in colon cancer, revealed its functions in intestinal cancer, and provided novel insights into the molecular mechanism of ADCK1 in regulating the Wnt/β-catenin signaling pathway." (PMID 33824271, 2021). "Then, EdU, soft agar and Transwell assays were performed to measure the impact of ADCK1 expression on the proliferation, colony formation and invasion abilities of colon cancer cells." (PMID 33824271, 2021). "Overexpression of ADCK1 in colon cancer cells activated the Wnt/β-catenin signaling pathway reporter gene, and the activity of the reporter gene was downregulated after ADCK1 expression was inhibited." (PMID 33824271, 2021). "In conclusion, this study identified the functions of ADCK1 in the progression of colon cancer and provided potential therapeutic targets." (PMID 33824271, 2021). "Here, we found an increase in ADCK1 (AarF domain-containing kinase 1) expression in clinical specimens of colon cancer and animal models." (PMID 33824271, 2021). "To study the expression pattern of ADCK1 in colon cancer, we collected colon cancer samples for immunohistochemical staining and scoring." (PMID 33824271, 2021). "Subsequently, we interfered with ADCK1 expression in colon cancer cells and examined the impact of downregulation of ADCK1 expression on the proliferation, colony formation, and invasion of colon cancer cells through EdU, soft agar colony formation, and Transwell assays." (PMID 33824271, 2021). "In this study, we found upregulation of ADCK1 in colon cancer samples." (PMID 33824271, 2021). "Moreover, knockdown of ADCK1 promoted the apoptosis of colon cancer cells." (PMID 33824271, 2021). "We also observed that the promotive effects of ADCK1 on cell invasion and anchorage-independent growth depended on the Wnt/β-catenin signaling pathway, indicating that ADCK1 promoted the malignant phenotypes of colon cancer cells by activating the Wnt/β-catenin signaling pathway." (PMID 33824271, 2021). "Therefore, we later selected two colon cancer cell lines, SW620 and RKO, for forced ADCK1 expression." (PMID 33824271, 2021).
osteosarcoma (3 papers, 2022 to 2025). A usually aggressive malignant bone-forming mesenchymal neoplasm, predominantly affecting adolescents and young adults. "In a study examining ADCK1 expression in osteosarcoma (OS) cells, researchers found that the knockout of ADCK1 led to significant disruptions in mitochondrial function." (PMID 40565246, 2025). "We here showed that ADCK1 (AarF domain-containing kinase 1), a mitochondrial protein, is upregulated in human osteosarcoma (OS) tissues and OS cells." (PMID 36371387, 2022). "This suggests that ADCK1 may function as an oncogene, playing a critical role in the development and progression of osteosarcoma." (PMID 40565246, 2025).
adenoma (1 paper, 2021). A neoplasm arising from the epithelium. "We first evaluated adenoma formation in this mouse model and examined ADCK1 expression in the adenomas using immunohistochemical staining." (PMID 33824271, 2021). "The experimental results showed that upregulation of ADCK1 had already occurred in early adenomas." (PMID 33824271, 2021). "We also assessed ADCK1 expression in early adenomas using a mouse adenoma model." (PMID 33824271, 2021). "Similarly, ADCK1 expression increased in early adenomas (P = 0.002)." (PMID 33824271, 2021).
breast carcinoma (1 paper, 2018). "Sixteen understudied kinases showed strong variance between TNBC and HER2/luminal breast cancer, with higher-ranked understudied kinases being DAPK3, ADCK1, MRCKA (CDC42BPA), STK17A, DMPK and VRK2." (PMID 29643987, 2018).
hyperparathyroidism (1 paper, 2023). Hyperfunction of the parathyroid glands resulting in the overproduction of parathyroid hormone. "The cohort was screened for gene variants of ADCK1, CCD1, FAT3, and THRAP3 that have previously been associated with PC as described in the literature but that were not included in the BpG hyperparathyroidism gene panel assessment." (PMID 36900197, 2023).
muscular disease (1 paper, 2019). Myopathy is a peripheral nervous system disease consisting of any abnormal condition or disease of the muscular tissues; commonly designates a disorder involving skeletal muscle. "As malfunctioning of the ADCK1 pathway was confirmed to induce muscular dysfunctions, our research will be of help in finding the mechanism of pathogenesis and treatments for mitochondria-related muscular diseases." (PMID 31125351, 2019).
pancreatic adenocarcinoma (1 paper, 2018). "ADCK1, DAPK3, DMPK STK17A and VRK2 were found to be similarly amplified in other cancers including prostate adenocarcinoma, uterine carcinosarcoma and pancreatic adenocarcinoma." (PMID 29643987, 2018).
parathyroid carcinomas (1 paper, 2021). "In unrelated, exome-based studies, recurrent mutations in AarF domain containing kinase 1 (ADCK1) and prune homolog 2 with BCH domain (PRUNE2) have been reported in parathyroid carcinomas; however, their functional roles has not been elucidated." (PMID 33269427, 2021).
schizophrenia (1 paper, 2025). A major psychotic disorder characterized by abnormalities in the perception or expression of reality. "A study examining the effects of paliperidone palmitate treatment in patients with schizophrenia (n = 159) found that the response to this treatment was influenced by polymorphisms in the ADCK1 gene." (PMID 40565246, 2025). "Genetic alterations in the ADCK1 gene have been linked to cases of schizophrenia." (PMID 40565246, 2025).
Sepsis (1 paper, 2025). Sepsis is defined as life-threatening organ dysfunction caused by a dysregulated host response to infection. "Notably, upregulation of ADCK1, IGF1R, and MAP3K1 at the transcriptional level was found to predict higher sepsis risk, while increased expression of BLK and KCNJ15 correlated with lower risk." (PMID 40761792, 2025).
Wilms tumour (1 paper, 2025). "Our results revealed a significant association between the rs6494 polymorphism and susceptibility to Wilms tumour development, and the protective allele A of rs6494 was associated with decreased expression of ALKBH1 and increased expression of SNW1 and ADCK1." (PMID 41017026, 2025).
cancer (5 papers, 2018 to 2025). A tumor composed of atypical neoplastic, often pleomorphic cells that invade other tissues. "Collectively, these findings indicate that the overexpression of ADCK1 contributes to a pro-cancerous phenotype, while its depletion or knockout exerts anti-cancer effects in OS cells." (PMID 40565246, 2025). "ADCK1 expression was found to be elevated in human OS tissues, suggesting a potential role in cancer progression." (PMID 40565246, 2025). "In vivo experiments have shown that knocking down ADCK1 inhibited the ability of cancer cells to form organoids and tumors, while also reducing metastasis." (PMID 40565246, 2025). "Conversely, stable and ectopic overexpression of ADCK1, using a lentiviral construct, exerted pro-cancerous activity in OS cells, promoting cancer cell proliferation and migration." (PMID 36371387, 2022). "Yet, low ADCK1 expression was detected in cancer-surrounding normal bone tissues and primary human osteoblasts." (PMID 36371387, 2022). "Downregulation of ADCK1 expression inhibited the colony formation and infiltration of cancer cells, in vivo tumorigenesis, migration, and organoid formation." (PMID 33824271, 2021). "Later, we evaluated ADCK1 expression in eight pairs of cancer tissues and paired paracarcinoma tissues." (PMID 33824271, 2021). "ADCK1 silencing or KO resulted in potent anti-cancer activity in cultured OS cells." (PMID 36371387, 2022). "Upregulation of ADCK1 expression promoted the colony formation and infiltration of cancer cells." (PMID 33824271, 2021). "ADCK1 promoted the in vivo tumor formation and metastasis of cancer cells." (PMID 33824271, 2021). "Therefore, ADCK1 shRNA or KO resulted in potent anti-cancer activity in cultured OS cells." (PMID 36371387, 2022). "Downregulation of ADCK1 expression inhibited the formation of organoids, which revealed that downregulation of ADCK1 expression might negatively control the Wnt/β-catenin signaling pathway and the stemness of stem cells, as a result, inhibiting the activity of cancer stem cells." (PMID 33824271, 2021). "It is not clear whether ADCK1 also affects the functions of mitochondria and behaviors of human cells, and whether its expression is altered in human cancer cells." (PMID 36371387, 2022).
tumor (3 papers, 2021 to 2025). "We also combined the ADCK1 blotting data of all 16 pairs of tissue specimens and found that ADCK1 protein expression in OS tumor tissues was significantly higher than that in normal bone tissues." (PMID 36371387, 2022). "As shown ADCK1 mRNA levels in OS tumor tissues (“T”) were significantly higher than those in the adjacent normal bone tissues (“N”)." (PMID 36371387, 2022). "The ADCK1 green fluorescence intensity in OS tumor slides was significantly higher than that in the normal bone tissue slides, further showing mitochondrial ADCK1 upregulation in the OS tissues." (PMID 36371387, 2022). "Significantly, ADCK1 protein in the mitochondrial lysates of OS tumor tissues was again upregulated." (PMID 36371387, 2022). "The results of the experiment with the clinical specimens indicated that the expression of ADCK1 was upregulated in tumor tissues." (PMID 33824271, 2021). "In the subcutaneous tumor formation assay, we found that downregulation of ADCK1 expression inhibited tumor formation in nude mice and reduced the volume and weight of the tumors." (PMID 33824271, 2021). "ATP contents were again depleted in the ADCK1 KO in situ tumor tissues." (PMID 36371387, 2022). "Seven of the eight pairs of tissues showed high expression of ADCK1 in the tumor tissues." (PMID 33824271, 2021). "Moreover, the expression of ADCK1 was correlated with the tumor stage, metastasis, and the outcome of the chemotherapy regimen." (PMID 33824271, 2021). "The functions of ADCK1 in tumor formation and development remain unknown." (PMID 33824271, 2021).
ADCK1 also shares sentences with these, for which no sentence is quoted: intestinal cancer (1 paper); lung carcinoma (1); neuroblastoma (1); Obesity (1); pancreatic cancer (1); prostate adenocarcinoma (1); psychiatric disorder (1); uterine carcinosarcoma (1).